NLRP3 (NLR family pyrin domain containing 3)
Diseases named in the same sentence as NLRP3 in open-access papers (continued):
Sharing a sentence is not in itself a finding about the gene and the disease.
diabetes (continued). "Many studies showed that hyperglycemia could produce excessive ROS and activate NF-κB, thereby triggering the activation of intracellular signal transduction and NLRP3 inflammasome in the occurrence and development of diabetes." (PMID 36248820, 2022). "However, the differences in the mode of NLRP3 inflammasome activation between different subpopulations of cardiac-resident macrophages and peritoneal macrophages in the context of diabetes are unclear, this requires further investigation." (PMID 36142531, 2022). "In STZ (streptozotocin)-induced hyperglycemia and hyperlipidemia in apoE −/− mice, metformin can suppress the development of diabetes-accelerated atherosclerosis and NLRP3 inflammasome activation, and this inhibitory effect can be abolished by AMPK inhibitor compound C." (PMID 36142531, 2022). "The NLRP3 inflammasome is involved in many diseases, including diabetes." (PMID 35563208, 2022). "It has been reported that H2S has both anti-inflammatory and pro-inflammatory effects, so whether H2S can promote the NLRP3 inflammasome in diabetes also remains to be studied." (PMID 35563208, 2022). "NLRP3 inflammasome-mediated inflammatory cytokines can act in both an autocrine and a paracrine manner and contribute to multiple chronic inflammatory diseases and metabolic disorders, such as obesity, hypertension, diabetes, atherosclerosis, and cancer." (PMID 35937790, 2022). "Activation of the NLRP3 inflammasome in the setting of diabetes mellitus and specifically in DKD has likewise been shown before The current data support the concept that endothelial dysfunction with impaired aPC generation promotes NLRP3 inflammasome activation and sterile inflammation in DKD." (PMID 35956315, 2022). "NLRP3 inflammasome mediated pyroptosis was confirmed as an important mechanism of diabetes." (PMID 35165294, 2022). "Diabetes and IR are influenced by NLRP3 levels, which could be used as anti-diabetes treatment targets." (PMID 36532503, 2022). "In addition, excessive ROS in diabetes have been found to trigger NOD-like receptor protein 3 (NLRP3) inflammasome activation in SCs." (PMID 36291547, 2022). "Moreover, in relation to diabetes, nod‐like receptor family pyrin domain‐containing protein‐3 (NLRP3) complex inflammasome has been identified to contribute to the development of both, periodontitis and diabetes." (PMID 35909305, 2022). "Interestingly, the effects of diabetes on cystitis are at least partially contributable to the increases in NLRP3, a regulator for IL-1β." (PMID 36405726, 2022). "We have previously shown that renal ischemia-reperfusion triggers cardiac arrhythmia through NLRP3 inflammasome activation and IL-1β production, and in diabetes mellitus, the NLRP3 inflammasome connects metabolic dysfunction to cardiac arrhythmias through IL-1β production." (PMID 36341442, 2022). "Additionally, NLRP3 inflammasome activation is enhanced in patients with newly diagnosed diabetes compared to healthy matched controls." (PMID 35563363, 2022). "Meanwhile, the elevated level of IL-1β further confirmed that ER-stress-related inflammatory pathways were activated by PA exposure, which was consistent with the reported studies describing the inflammatory NLRP3 pathway that interacts with ER stress pathways in diabetes." (PMID 35565803, 2022). "Therefore, corilagin possesses excellent potential to treat NLRP3-dependent inflammatory diseases such as gout, diabetes, sepsis, and cancer." (PMID 36299604, 2022). "Therefore, the role of H2S in regulating the NLRP3 inflammasome/ERS or NLRP3 inflammasome/autophagy in diabetes is worth studying." (PMID 35563208, 2022). "Further studies need to deepen the research on the effect of NLRP3 inhibition in diabetes." (PMID 35055149, 2022). "Besides, the expression of NEK7 and the NLRP3 inflammasome was found to be significantly increased in arteries from patients with diabetic foot, with vascular smooth muscle cells showing the greater expression." (PMID 35204152, 2022).
diabetes (continued). "Finally, the current donor of exogenous H2S is not ideal; therefore, the development of better H2S donors will be more conducive to the application of H2S in the regulation of the NLRP3 inflammasome in diabetes." (PMID 35563208, 2022). "The H2S/NLRP3 inflammasome has been involved in diabetes in many studies, respectively, but the roles and the mechanisms of the two in the occurrence and development of diabetes need to be further elucidated." (PMID 35563208, 2022). "The NLRP3 inflammasome is an important component of pathological inflammation that can trigger local and systemic inflammation; it has crucial roles in various diseases (e.g., autoimmunity, diabetes, and cardiovascular disease)." (PMID 35784553, 2022). "NLRP3 inflammasome dysfunction can contribute to many diseases, including diabetes." (PMID 35563208, 2022). "Therefore, a well‐known NLRP3 inhibitor, colchicine, appears to be promising to be repurposed for the treatment of COVID‐19, especially in patients with concurrent obesity or diabetes." (PMID 34970856, 2022). "It was found that NLRP3 silencing improved myocardial inflammation, fibrosis, and cardiac dysfunction in type ii diabetic mice induced by high glucose, suggesting that the reduction of pyroptosis can improve the complications of diabetes." (PMID 35647057, 2022). "Thus, NLRP3 inflammasome is proposed to be a potential novel therapeutic target of inflammation related chronic diseases including diabetes." (PMID 34631209, 2021). "Therefore, this study investigated the effects of NAG-1 overexpression on NLRP3 inflammasome component expression in a mouse model of HFD/STZ-induced diabetes." (PMID 34294853, 2021). "Furthermore, we try to indicate the role of diabetes in CCS and the link of NLRP3 inflammasome between diabetes and CCS." (PMID 34512671, 2021). "It suggests that environmental endocrine disruptors play an important role in the inflammation of islet beta cells and may contribute to the development of diabetes through NLRP3 inflammatory signaling." (PMID 34055976, 2021). "It has been observed that glyburide, a drug for the treatment of diabetes classified as a sulfonylurea, may block the activation of the NLRP3 inflammasome through the inhibition of ATP-sensitive K+ channels." (PMID 33466589, 2021). "Recent studies have revealed that nucleotide-binding and oligomerization domain-like receptor family pyrin domain-containing 3 (NLRP3) inflammasome plays a vital role in the progression of diabetes and many of its complications, making it a promising therapeutic target in pharmaceutical design." (PMID 34631209, 2021). "Since MCD-fed mice recapitulate the histology of human NAFLD (hepatic steatosis, and fibrosis) but lack the metabolic component (obesity, high cholesterol and diabetes) to assess the impact of metabolic imbalances in NLRP3 activation in NASH, ApoE-/- mice were fed with WD." (PMID 34513923, 2021). "However, the mechanism of the effects of ERS on NLRP3 inflammasome in diabetes has not been fully understood." (PMID 33937267, 2021). "Studies have shown that ERS can regulate NLRP3 inflammasome in many diseases including diabetes." (PMID 33937267, 2021). "Moreover, high expression of NLRP3 and caspase-1 was found in cardiac fibrosis tissue of rats with diabetes." (PMID 35145423, 2021). "Thus, the NLRP3 inflammasome plays an important role in kidney diseases through its regulation of the inflammatory response in diabetes." (PMID 34326777, 2021).
diabetes (continued). "On the basis of preceding awareness pertaining to antidiabetic agents used for managing Type 2 diabetes mellitus and utilizing the NLRP3 inflammasome suppressive effects of MCC950 (CRID3) in nanomolar concentrations, a fascinating assemblage of nine crossbreed compounds have been advanced." (PMID 34443594, 2021). "Activation of the diabetes-mediated pyroptosis-related inflammasomes, such as nucleotide-binding oligomerization domain-like receptor protein 3 (NLRP3), Toll-like receptor 4 (TLR4), caspase-1, interleukin (IL)-1β, and the IL-18 axis, plays an essential role in DKD lesions." (PMID 33692782, 2021). "In this review, ERS activates NLRP3 inflammasome through the ROS/TXNIP pathway in diabetes." (PMID 33937267, 2021). "Thus, our results indicated that THJ inhibited activation of the NLRP3 inflammasome, which was induced by diabetes." (PMID 33637069, 2021). "Many studies have shown that the NLRP3 inflammasome can regulate IL-1β activation in diabetes." (PMID 33637069, 2021). "Importantly, as the key element of inflammation, NOD-like receptor pyrin domain containing 3 (NLRP3) inflammasome is indicated to play an important role in diabetes, stroke, and the sequential CCS." (PMID 34512671, 2021). "NLRP3 inflammasome has been shown to initiate and participate chronic complications of diabetes." (PMID 34707607, 2021). "They concluded that the ROS-dependent activation of endothelial NLRP3 inflammasome by hyperglycemia might be essential to initiate the mechanism provoking endothelial dysfunction and endothelial injury in diabetes." (PMID 33546399, 2021). "In the hyperglycemic environment, the increase in NLRP3 inflammasome-dependent IL-1β secretion leads to the dysfunction of insulin secretion of β cells, promotes obesity and insulin resistance, and eventually leads to diabetes." (PMID 33937267, 2021). "Despite a great variety of molecules used in several diabetes animal models to reduce NLRP3/AIM2 inflammasome activation, and hence, to prevent cardiac injury, clinical trials are still required to study the possible benefit of NRLP3 targeted therapies in humans." (PMID 35004869, 2021). "Similarly, in osteoclasts exposed to high concentrations of glucose and the rat model of diabetic OP, the expression levels of NLRP3 inflammasome and its related proteins are increased, bone density is reduced, and osteoclast markers are increased." (PMID 34646239, 2021). "LncRNAs regulating NLRP3 inflammasome in diabetes complications." (PMID 35087834, 2021). "Aberrant activation of NLRP3 inflammasome is closely related to the development of various diseases, including inflammatory diseases, infections, Alzheimer's disease, and diabetes." (PMID 34335089, 2021). "Importantly, NLRP3 inflammasome activation plays an indispensable role in diabetes and diabetic complications." (PMID 34512671, 2021). "Mitochondrial DNA activates NLRP3 inflammasome in endothelial cells via Ca2+ influx and mitochondrial ROS generation, which mediates endothelial dysfunction and vascular inflammation in diabetes complications." (PMID 34707607, 2021). "The inhibition of miR-223, a miRNA expressed in diabetes, downregulates the markers of inflammation (NLRP3), fibrosis (collagens I and III), and apoptosis (caspase-3 and Bax), attenuating the cardiac effects as well in the systolic function and ventricular remodeling of STZ-induced diabetes." (PMID 35004869, 2021). "Recent studies have indicated the role of NLRP3 inflammasome in diabetes and diabetic CCS." (PMID 34512671, 2021). "Hyperglycemia and hypoxia observed during problematic ventilation of patients with diabetes and undergoing a SARS-CoV-2 infection promote the production of ROS, which may cause NLRP3-mediated pyroptosis." (PMID 33466589, 2021).
diabetes (continued). "We characterize the ways of NLRP3 inflammasome activation and the subsequent cardiac pathological damage in CCS combined with diabetes and propose that NLRP3 inflammasome-mediated inflammation may be a potential target in diabetic CCS." (PMID 34512671, 2021). "NLRP3 inflammasome inhibition has been reported to improve diabetes-mediated cognitive impairment." (PMID 34356130, 2021). "These researches imply that NLRP3 inhibitors could serve as a potential target for patients with diabetes." (PMID 34707607, 2021). "A possible mechanism may be that in T2DM NLRP3 inflammasome action is upregulated leading diabetes to be a state of low-grade inflammation." (PMID 33329516, 2020). "Finally, alteration of NLRP3 pathway is involved in other diseases including diabetes, Alzheimer disease, gout, rheumatoid arthritis, or asthma." (PMID 32849554, 2020). "Moreover, activity of NLRP3 inflammasome pathway was significantly increased in patients with AS and diabetes at the early stage of plaque formation." (PMID 32966239, 2020). "In this work, we sought to characterize whether MFG-E8 regulates “NLRP3 inflammasome-NETs” loop to promote wound healing in diabetes." (PMID 32963812, 2020). "In this study, we further examine whether high concentration of glucose, mimics the hyperglycemia environment of diabetes patients, stimulates vascular calcification through the NLRP3 inflammasome system." (PMID 31938471, 2020). "NLRP3 plays an important role in the development of diabetes." (PMID 32166013, 2020). "In general, inhibition of the NLRP3 inflammasome can slow the occurrence of pyroptosis in diabetes and related complications, which may be the key to preventing and slowing the development of DN." (PMID 32456088, 2020). "To summarize, our study provided evidence that punicalagin can alleviate diabetic nephropathy, and the effect is associated with downregulating the expression of NOX4, inhibiting TXNIP/NLRP3 pathway-mediated pyroptosis, suggesting its therapeutic implications for complications of diabetes." (PMID 32456088, 2020). "The results concerning the antagonized role of 6-shogaol might lead to the design and development of ginger-containing dietary therapy and/or new drugs for treating vascular calcification complication of diabetes through targeting the NLRP3 inflammasome." (PMID 31938471, 2020). "Indeed, individually targeting NF‐κB and the NLRP3 inflammasome have been shown to be efficacious in protecting against microvascular disease in diabetes." (PMID 32608058, 2020). "The activation of abundantly expressed NLRP3 inflammasome represents the background process of the diabetes mellitus disturbances like hyperglycemia and insulin resistance, as well as for myocardial cell death and fibrosis, all of them being features characteristic for cardiometabolic syndrome." (PMID 33172097, 2020). "The present study provides evidence that inflammatory responses become increasingly amplificative through “NLRP3 inflammasome-NETs” inflammatory loop in wound site of diabetes, and the “NLRP3 inflammasome activation-NETs formation” loop contributes to delayed wound healing in diabetes." (PMID 32963812, 2020). "In type-2 diabetes patients, NLRP3 inflammasome activation is higher in myeloid cells, and NLRP3 inflammasome inhibitors might be clinically useful in treating ischemic stroke concomitant with diabetes." (PMID 33584697, 2020). "Although we focused on NLRP3 since it is activated in burn tissue and metabolic disease states (e.g., diabetes and obesity), we cannot exclude the fact that other NLRs could be involved and could compensate for inhibition of NLRP3 activation." (PMID 32750036, 2020). "The association of NLRP3 with RCC and diabetes needs further investigation." (PMID 32313131, 2020).
diabetes (continued). "Vitamin D3 decreases diabetes induced Reactive Oxygen Species (ROS) and exerts protective effects against retinal vascular damage and cell apoptosis in association with the inhibition of the ROS/TXNIP/NLRP3 inflammasome pathway." (PMID 33633656, 2020). "Our data support the tenet that RIPK3 may mediate diabetes-induced fibrosis through the NLRP3 inflammasome." (PMID 32591618, 2020). "H2S has therapeutic effect on diabetes through inhibiting NLRP3 inflammasome." (PMID 33110394, 2020). "Second, MFG-E8 inhibits active NLRP3 inflammasome-primed NETs formation in diabetes." (PMID 32963812, 2020). "Innate immune signaling through the NLRP3 inflammasome is activated by multiple diabetes-related stressors, but whether targeting the inflammasome is beneficial for diabetes is still unclear." (PMID 32968070, 2020). "Notably, AMPK activation attenuates NLRP3 inflammasome upregulation in some pathological processes, such as diabetes, pain, ischemic stroke, and endoplasmic reticulum stress." (PMID 32848777, 2020). "Although there have been only animal (mouse) experiments to verify the role of NLRP3 in the diabetic-stroke brain, NLRP3 inflammasome inhibitors may likely mitigate the disease outcome of patients with ischemic stroke concomitant with diabetes." (PMID 31174550, 2019). "Since NLRP3 inflammasome activation and endothelial dysfunction are also important pathophysiological steps in diabetes and cardiovascular diseases, PCB2 may exert pleiotropic effects in vivo." (PMID 31440258, 2019). "Obesity can promote the priming signals toward NLRP3 inflammasome formation in diabetes." (PMID 31174550, 2019). "Measures taken against NLRP3 inflammasome activity may be used to treat ischemic stroke that is concomitant with diabetes." (PMID 31174550, 2019). "Studies suggest that inhibition of NLRP3 prevents or alleviates both ischemic stroke and diabetes." (PMID 31174550, 2019). "The nucleotide binding oligomerization domain-like receptor protein 3 (NLRP3) inflammasome, the key component of pyroptosis, is involved in inflammation reaction, which may be one of the important mechanisms in diabetes-induced myocardial injury." (PMID 31871948, 2019). "However, many reports refer to the activation of the NLRP3 inflammasome in peripheral tissues in diabetes." (PMID 31197747, 2019). "Numerous evidence suggests that NLRP3 inflammasome activation may regulate the inflammation process of diabetes mellitus and related complications." (PMID 31859818, 2019). "In addition, we found that the interaction between Kir6.1 and NLRP3 was reduced in response to NLRP3 agonists such as ATP or under the conditions of diabetes." (PMID 31387986, 2019). "There are evidences suggesting that effective regulation or inhibition of NLRP3 may help prevent or treat either ischemic stroke or diabetes when separated." (PMID 29853850, 2018). "In diabetes, hyperglycemia can activate ROS and NLRP3 inflammasome." (PMID 30114208, 2018). "Interestingly, the effects of saxagliptin on the NLRP3 inflammasome components and subsequent kidney remodeling were comparable in both type 1 and type 2 murine models of diabetes." (PMID 29515457, 2018). "However, our study also has some limitations; for example, the experimental animal models we chose are simple, and we should use a variety of diabetes animal models for further investigation of the role of the NLRP3 inflammasome in DEP." (PMID 29495433, 2018). "However, there remain many questions, especially regarding cross-talk networks between NLRP3 inflammasome activation and the physiological course of diabetes concomitant with ischemic stroke." (PMID 29853850, 2018). "It is believed that NLRP3 inflammasome may become a potential drug target for the treatment of ischemic stroke combined with diabetes mellitus." (PMID 29853850, 2018).